RAD51B (RAD51 paralog B)
Description:
Involved in the homologous recombination repair (HRR) pathway of double-stranded DNA breaks arising during DNA replication or induced by DNA-damaging agents. May promote the assembly of presynaptic RAD51 nucleoprotein filaments. Binds single-stranded DNA and double-stranded DNA and has DNA-dependent ATPase activity. Part of the RAD51 paralog protein complex BCDX2 which acts in the BRCA1-BRCA2-dependent HR pathway. Upon DNA damage, BCDX2 acts downstream of BRCA2 recruitment and upstream of RAD51 recruitment. BCDX2 binds predominantly to the intersection of the four duplex arms of the Holliday junction and to junction of replication forks. The BCDX2 complex was originally reported to bind single-stranded DNA, single-stranded gaps in duplex DNA and specifically to nicks in duplex DNA. The BCDX2 subcomplex RAD51B:RAD51C exhibits single-stranded DNA-dependent ATPase activity suggesting an involvement in early stages of the HR pathway.
Synonyms: R51H2; RAD51L1; REC2; hREC2
Tractability: Small molecule: a structure with a bound ligand is known. PROTAC: ubiquitination databases record sites on it.
Gene: Protein-coding gene on chromosome 14 (67,819,779 to 68,730,218, forward strand). Ensembl gene ENSG00000182185.
Subcellular location: Nucleus
Subcellular location (Human Protein Atlas): Nuclear bodies; Nucleoplasm
Pathways (Reactome):
DNA Repair: HDR through Homologous Recombination (HRR); Homologous DNA Pairing and Strand Exchange; Presynaptic phase of homologous DNA pairing and strand exchange; Resolution of D-loop Structures through Holliday Junction Intermediates; Resolution of D-loop Structures through Synthesis-Dependent Strand Annealing (SDSA)
Disease: Defective HDR through Homologous Recombination Repair (HRR) due to PALB2 loss of BRCA1 binding function; Defective HDR through Homologous Recombination Repair (HRR) due to PALB2 loss of BRCA2/RAD51/RAD51C binding function; Defective homologous recombination repair (HRR) due to BRCA1 loss of function; Impaired BRCA2 binding to PALB2
Hemostasis: Factors involved in megakaryocyte development and platelet production
Gene Ontology:
Molecular function: ATP-dependent activity, acting on DNA; double-stranded DNA binding; four-way junction DNA binding; protein binding; single-stranded DNA binding; DNA binding; ATP binding; ATP-dependent DNA damage sensor activity
Biological process: double-strand break repair via homologous recombination; positive regulation of G2/M transition of mitotic cell cycle; supramolecular fiber organization; DNA recombination; DNA repair; reciprocal meiotic recombination
Cellular component: Rad51B-Rad51C-Rad51D-XRCC2 complex; replication fork; nucleoplasm; nucleus
Genetic constraint (gnomAD): Loss-of-function variants: 31 observed, 33.56 expected, observed/expected ratio (o/e) 0.92, 90% interval 0.69 to 1.25. The upper end of that interval is the gene's LOEUF score, 1.25, which puts it in group 5 of 6, group 1 being the genes least tolerant of losing a copy. Missense variants: 341 observed, 380.23 expected, observed/expected ratio (o/e) 0.9, 90% interval 0.82 to 0.98. Synonymous variants: 145 observed, 142.87 expected, observed/expected ratio (o/e) 1.01, 90% interval 0.89 to 1.16.
Homologues: Orthologues: chimpanzee RAD51B (99% identical), macaque RAD51B (97% identical), dog RAD51B (90% identical), pig RAD51B (89% identical), rabbit RAD51B (88% identical), mouse Rad51b (85% identical), rat Rad51b (83% identical), guinea pig RAD51B (63% identical), zebrafish rad51b (56% identical). Paralogues in human: RAD51C (28% identical), XRCC3 (27% identical), RAD51D (24% identical), RAD51 (23% identical), DMC1 (23% identical), XRCC2 (17% identical).
Diseases named in the same sentence as RAD51B in open-access papers:
RAD51B is named in the same sentence as 93 diseases in open-access papers, as found by Europe PMC text mining. Sharing a sentence is not in itself a finding about the gene and the disease. The quoted sentences say what the papers report.
breast carcinoma (49 papers, 2010 to 2025). "Consistently, high expression of RAD51B has been found to be associated with a favorable prognosis for breast cancer and lung cancer." (PMID 37858068, 2023). "For both ESR1 and RAD51B our decorrelation approach was the only one that concluded a statistically significant association between SNP-set in those genes with breast cancer." (PMID 32287273, 2020). "Studies of variants in RAD51B revealed statistically significant associations of SNPs in RAD51B with breast cancer occurrence." (PMID 31191752, 2019). "Pathogenic variants were identified in CHEK2, MUTYH, and RAD51B in four breast cancer patients, which represented 8.3% of the cohort." (PMID 31780696, 2019). "A RAD51B truncating variant p.Arg47* was observed in a family characterized by early onset breast cancer and colorectal cancer." (PMID 31780696, 2019). "BARD1, PALB2, and RAD51B variants have been identified in breast cancer families, whereas truncating RAD51C and RAD51D variants are mainly found in families with ovarian cancer or breast and ovarian cancer." (PMID 30689231, 2019). "Researchers have proposed that LoF variants in RAD51B (RAD51L1) confer a high risk of breast cancer, but it remains inconclusive owing to the extreme rarity of the LoF mutations (only 48 carriers in 60,706 participants in ExAC; carrier frequency, 0.08%)." (PMID 29316957, 2018). "Recently, a few researches have focused on a genetic level to study the association between RAD51B genetic variants and the risk of the male breast cancer in a GWAS study, and the association with death risk of glioblastoma in a case-control study." (PMID 29207658, 2017). "Our results suggest that loss-of-function mutations in RAD51B are rare, but common variation at the RAD51B region is significantly associated with familial breast cancer risk." (PMID 27149063, 2016). "RAD51B is a plausible candidate gene for the association as it functions in HR repair of DNA damage like most of the known breast cancer genes." (PMID 27149063, 2016). "To study the role of RAD51B in breast cancer predisposition, we screened the coding sequence in 172 Finnish breast or ovarian cancer patients." (PMID 27149063, 2016). "To identify putative recurrent founder mutations and to study the role of RAD51B in female and male breast cancer predisposition and especially in familial breast cancer, we comprehensively screened the RAD51B gene in 172 Finnish cancer patients." (PMID 27149063, 2016). "The major-allele of the common polymorphism rs999737 in intron 10 of RAD51B and the minor-allele of rs2588809 in intron 7 have been associated with an increased risk of female breast cancer." (PMID 27149063, 2016). "Common variation on 14q24.1, close to RAD51B, has been associated with breast cancer: rs999737 and rs2588809 with the risk of female breast cancer and rs1314913 with the risk of male breast cancer." (PMID 27149063, 2016). "The aim of this study was to investigate the role of RAD51B variants in breast cancer predisposition, particularly in the context of familial breast cancer in Finland." (PMID 27149063, 2016). "Out of the common variants at the RAD51B region, rs999737 and rs2588809 have been associated with female breast cancer and rs1314913 with male breast cancer." (PMID 27149063, 2016). "Variants in the RAD51B region, also known as RAD51L1, have been associated with breast cancer risk in genome-wide association studies (GWAS)." (PMID 27149063, 2016). "While germline mutations in RAD51C and RAD51D are associated with high ovarian cancer risk and RAD51B polymorphisms with breast cancer, the contribution of RAD51, XRCC3, and XRCC2 is more unclear." (PMID 25918678, 2015). "Deleterious germline mutations in the RAD51C and RAD51D genes confer an increased risk of ovarian cancer whereas common polymorphisms in the RAD51B gene are associated with male and female breast cancer." (PMID 25918678, 2015).
breast carcinoma (continued). "In the case of the RAD51B gene, a correlation has been demonstrated between the presence of the rs3784099 polymorphism and the risk of breast cancer." (PMID 26339569, 2015). "These mutations and variants were detected in families with both breast and ovarian cancers, except for the RAD51B c.475C > T/p.Arg159Cys variant that occurred in a family with 3 breast cancer cases." (PMID 24139550, 2013). "Mutations and likely deleterious variants were detected in families with both breast and ovarian cancers, except for the RAD51B p.Arg159Cys variant that occurred in a family with 3 breast cancer cases." (PMID 24139550, 2013). "RAD51B, a gene involved in encoding proteins that participate in DNA repair, has been linked to breast cancer and brain cancer." (PMID 24481203, 2013). "We identified a RAD51B mutation and a likely deleterious variant in two patients: the RAD51B c.452 + 3A > G mutation was detected in a breast and ovarian cancer family case and the RAD51B p.Arg159Cys variant was detected in a family with 3 breast cancer cases." (PMID 24139550, 2013). "These include Rad52, the human Rad51 paralogs Rad51B, Rad51C, Rad51D, Xrcc2, and Xrcc3, and breast cancer susceptibility gene Brca2." (PMID 21129202, 2010). "Given the rarity of loss-of-function germline RAD51B variants, our study had limited statistical power to assess an association between RAD51B inactivation and hormone receptor status among breast cancer cases, and additional cases will be required to confirm the association." (PMID 34635660, 2021). "Thus, we focused on an AGATCA core motif of a 9 bp palindromic sequence in intron 10 of RAD51B, which was originally reported to be specifically mutated in breast cancer." (PMID 33049910, 2020). "Furthermore, our results reveal that SNPs located on the RAD51B gene are significantly associated with an abnormal regulatory activity, suggesting a pivotal role for homologous recombination repair mechanisms in breast cancer." (PMID 32850701, 2020). "When combined with GWAS evidence, our results suggest that RAD51B may be a candidate that warrants reconsideration for inclusion in breast cancer susceptibility gene panels." (PMID 31780696, 2019). "We also identified recurrent mutations within an intron of RAD51B in several breast cancer samples." (PMID 28056774, 2017). "In particular, RAD51B is a known breast cancer-associated gene." (PMID 28569218, 2017). "However, the common variants in the RAD51B region are associated with an increased breast cancer risk." (PMID 27149063, 2016). "Similarly, low-penetrance variants at the RAD51L1 locus (also known as RAD51B) have recently been associated with breast cancer (see further below)." (PMID 24025454, 2013). "Interestingly, other studies have reported that SNP in RAD51B was significantly associated with breast cancer risk in males, suggesting that RAD51B may be a common key factor in gender associated cancers." (PMID 30482241, 2018). "However, the risk implication of RAD51B variants seems to be an exception, which has been robustly replicated in different studies on breast cancer 5, 6, 7, 8, nasopharyngeal carcinoma 9, glioma 10, and cutaneous melanoma 11, suggesting the significant role of RAD51B variants in cancer risk." (PMID 27334422, 2016). "In addition, the known RAD51B risk SNPs rs999737, rs2588809, and rs1314913 and RAD51B haplotypes were studied in the previously published 40 studies participating in the Breast Cancer Association Consortium (BCAC) including 44,791 breast cancer cases and 43,583 controls." (PMID 27149063, 2016). "A positive correlation between RAD51B and ERα protein expression was observed in human breast cancer." (PMID 41318657, 2025). "The results showed that RAD51B expression in human or mouse TNBC cells was relatively lower than in other subtypes of breast cancer cell lines." (PMID 41318657, 2025). "We therefore examined the levels of RAD51B and ERα in tissue microarrays from 136 breast cancer patient samples." (PMID 41318657, 2025).
breast carcinoma (continued). "Kaplan–Meier plot of patients with basal-like breast cancer also showed that patients with lower levels of RAD51B have a worse probability of survival compared to patients with higher levels of RAD51B." (PMID 41318657, 2025). "To exclude the system interference in HP5008 cells, we conducted CRISPR-Cas9 knockouts of Rad51b, Ezh2, Suz12 and Aebp2 in Brca1-mutant 545 cells, which were isolated from a primary mammary tumor of a Brca1-MSK mouse." (PMID 41318657, 2025). "Somatic homozygous deletion, labeled as deep deletion, were observed in BRCA2 in a single breast cancer patient and in pancreatic cancer (RAD51B (n = 2), RAD51C (n = 2) and XRCC2 (n = 1))." (PMID 35783256, 2022). "The average age of breast cancer diagnosis in RAD51B carriers was 49 (range 30–61), and ovarian cancer diagnosis was 67.3 (range 58–79)." (PMID 34635660, 2021). "We sequenced the coding region of RAD51B in 168 Finnish breast cancer patients from the Helsinki region for identification of possible recurrent founder mutations." (PMID 27149063, 2016). "Moreover, RAD51B deletion enhanced the capacity of breast cancer cells to form secondary tumors in immunodeficient mice." (PMID 41318657, 2025). "Altogether, these data highlight the essential role of RAD51B in preserving ERα-positive cell identity and may contribute to lineage commitment switches in breast cancer." (PMID 41318657, 2025). "Altogether, these data demonstrate that RAD51B is essential for maintaining ERα-positive cell identity and might contribute to the switch of lineage commitment in breast cancer cells." (PMID 41318657, 2025). "Additionally, a positive correlation between RAD51B and ERα protein expression was observed in 136 breast cancer patient samples." (PMID 41318657, 2025). "Other genes with moderate, low, or uncertain penetrance that have been implicated in breast cancer, RECQL, RAD51B, ERCC3, MRE11A, RAD51D, BARD1, and NBN, had a yield of 0.3% (n = 7), 0.3% (n = 7), 0.3% (n = 6), 0.3% (n = 6), 0.2% (n = 4), 0.2% (n = 4), and 0.1% (n = 3), respectively." (PMID 35971132, 2022). "To showcase our method, we evaluate associations between breast cancer susceptibility and SNPs in estrogen receptor alpha (ESR1), fibroblast growth factor receptor 2 (FGFR2), RAD51 homolog B (RAD51B), and TOX high mobility group box family member 3 (TOX3) genes, without access to raw genotype data." (PMID 32287273, 2020). "Together with the previously cited reports, our data support RAD51B as a plausible candidate gene in breast cancer families, especially breast and ovarian cancer families, and it may also play a role in melanoma predisposition." (PMID 29316957, 2018). "However, 50% (10/20) of Rad51b loss-of-function somatic mutation patients were diagnosed with basal-like breast cancer, which is significantly increased a lot when compared to non-carriers." (PMID 41318657, 2025). "In addition, we studied the known rs999737, rs2588809, and rs1314913 SNPs and RAD51B haplotypes in 44,791 breast cancer cases and 43,583 controls from 40 studies participating in the Breast Cancer Association Consortium (BCAC) that were genotyped on a custom chip (iCOGS)." (PMID 27149063, 2016). "In human breast cancer MCF-7 cells, dox-induced RAD51B knockout reduced AMPK phosphorylation and EZH2 phosphorylation at Thr311, leading to decreased ERα expression." (PMID 41318657, 2025). "Our in vitro validation showed that Rad51b deletion affects the expression of ERα in mouse Fgfr2-mutant HP5008 cells, Brca1-mutant 545 cells, and the human breast cancer MCF-7 cells." (PMID 41318657, 2025). "Additionally, we observed a significant positive correlation between RAD51B expression and ESR1 downstream target enrichment in human breast cancer cell lines." (PMID 41318657, 2025). "Moreover, in human breast cancer MCF-7 cells, RAD51B deletion downregulated ERα expression and enhanced tamoxifen sensitivity." (PMID 41318657, 2025).
breast carcinoma (continued). "Importantly, through animal models and patient-derived organoid models, we demonstrated that targeting RAD51B downstream signaling with EZH2i re-induces functional ERα protein expression in ERα-negative breast cancer, thereby rendering tumors targetable by tamoxifen." (PMID 41318657, 2025). "Our findings demonstrated that depletion of RAD51B by CRISPR/Cas9 enhanced the recruitment of PRC2 to Esr1 promoter and resulted in the modification of H3K27me3 in this region, leading to the repression of ERα protein and the switch from ERα-positive breast cancer to an ERα-negative type." (PMID 41318657, 2025).